HSPA1A (heat shock protein family A (Hsp70) member 1A)
Diseases named in the same sentence as HSPA1A in open-access papers (continued):
Sharing a sentence is not in itself a finding about the gene and the disease.
cancer (73 papers, 2009 to 2026). A tumor composed of atypical neoplastic, often pleomorphic cells that invade other tissues. "Again, the FLNA editing state affected the expression of proliferation-, cancer-, and stress response–associated genes (Junb, Jun, Pard6b, Atf3, Hspa1a and -b, Cyp2c55, and Abcb1a)." (PMID 40471139, 2025). "Among those predictors, HSPA1A is better known to be associated with other types of cancers, with some indications for OC30,31." (PMID 33686173, 2021). "We found that KIAA0100 regulates cancer cells’ resistance to anoikis by its close association with the stress protein HSPA1A." (PMID 29867023, 2018). "Additionally, HSPA1A has been implicated in the evasion of immune surveillance, allowing cancer cells to escape immune recognition and destruction." (PMID 37993485, 2023). "The interaction of HspA1A (and other molecular chaperones) with cellular and organelle membranes and lipids has received a lot of attention in recent years because of the chaperones’ association with cancer." (PMID 30999671, 2019). "Overexpression on malignant neoplasm in a similar way to HSPA1A has made HSP90 and related protein networks an important object of research in molecular oncology." (PMID 41369326, 2025). "Increasing evidence emphasizes extracellular HSPA1A as an important player in mediating immune responses in cancer by either exerting pro- or anti-tumorigenic functions." (PMID 39684914, 2024). "The majority of HSP70 is constitutively expressed mainly in the cytoplasm and nucleus, but HSPA1A expression increases under stress and extracellular HSPA1A has been identified in cancers." (PMID 39684914, 2024). "A single-cell pan-cancer study last year detected a novel CD4+/CD8+ T-cell subtype characterized by a high expression of heat shock protein genes such as HSPA1A, HSPA1B, and other stress-response-related genes, known as the stress response (TSTR)." (PMID 38629070, 2024). "The mechanism of action was defined through upregulation of heat shock proteins HspA1A, Hsp70, Hsp90α, or Hsp105 and triggering apoptosis in human cancer cells." (PMID 37511896, 2023). "HSPA1A, a cytosolic molecular chaperone, embeds in the PM of cancer and stressed cells, and these cells actively secrete the protein to the EM." (PMID 35740982, 2022). "Within the cancer group, women ≥ 50 and of mixed race had the highest HSPA1A levels (p = 0.0183 vs. White women)." (PMID 35906272, 2022). "This knowledge would provide the necessary tools to manipulate HSPA1A’s unconventional PM and EM presence toward sensitizing cancer cells to therapies and activating the immune system against them." (PMID 35740982, 2022). "This information will allow the design of experiments to specifically deplete selected lipids from different parts of the endo/lysosomal pathway and determine the stress-induced or cancer-related changes that trigger HSPA1A’s recruitment to the PM and EM." (PMID 35740982, 2022). "HSPA1A exerts its chaperoning and anti-apoptotic functions in the cytosol of stressed and cancer cells." (PMID 35740982, 2022). "One of these Hsp70s is the stress-induced HSPA1A, which is overexpressed after stress, e.g., heat shock, and in several pathophysiological conditions, like cancer." (PMID 35740982, 2022). "Hspa1a belongs to the heat shock protein 70 (HSP70) family and is implicated in cancer development and drug sensitivity." (PMID 34858604, 2021). "Both cancer and normal cells showed the increased mRNA expression of hspa1a, with this increase being greater in normal cells." (PMID 34728686, 2021). "Hsp70 (HSPA1A) is often overexpressed in cancer cells, correlating with aggressiveness and poor prognosis for patients." (PMID 34199046, 2021). "One of the abundant exosomal and microvesicular markers is a heat shock protein 70 kDa (Hsp70, HSPA1A) that is ubiquitously expressed in cancer cells, most often indicating poor prognosis." (PMID 34716378, 2021).
cancer (continued). "Recent research revealed that HspA1A translocates to the PM and is presented in the cell surface of multiple cancer types resulting in radiation insensitive and aggressive tumors." (PMID 32825419, 2020). "HspA1A, a molecular chaperone, translocates to the plasma membrane (PM) of stressed and cancer cells." (PMID 32825419, 2020). "A number of gene nodes linked to drug resistance in other cancer types (including CAT, TRIM59, ANXA2, ADM, AJUBA, HSPA1A/1B, LAMC2, TRIM14, KRT8, KRT18, KRT9, CLDN1, and SMARCA2) were also down-regulated in PARPis-sensitive AsPCs." (PMID 33213473, 2020). "Although these combined observations strongly imply that HspA1A spans the PM, leaving a region of the protein in the extracellular space, they do not clarify why the embedding is highly increased in stressed and cancer cells." (PMID 30999671, 2019). "In agreement with previous studies, our results solidify the notion that HspA1A translocates and anchors to the PM of stressed and cancer cells, making it a conserved property of this important molecular chaperone." (PMID 30999671, 2019). "When exposed to OXA, significantly increased HSP70 1A [HSPA1A] gene expression was demonstrated again at the initial time point (0.5 hours: FD 43.9) as well as the next interval (24 hours: FD 2.4) in SW480 cancer cells." (PMID 29403306, 2017). "One recognition structure which has significant potential as a target recognition structure in cancer is a membrane form of the 70 kDa heat shock (stress) protein family of molecules (heat shock protein 70, Hsp70, HSPA1A)." (PMID 25165986, 2014). "Three different siRNAs or siRNA pools each for HSPA1A/HSPA1B and HSPA8 and, in addition, siRNA pools against HSPA2, which is expressed in a tissue specific manner and was implicated in cancer cell survival, and HSPA5 were utilized." (PMID 24265689, 2013). "Analysis of the HSPA1A promoter using the UCSC Genome Browser revealed that it lies within a CpG island that is methylated in other cancer cell lines." (PMID 23874968, 2013). "It was found that cancer cells demonstrating membrane-bound HspA1A stimulated the migration and cytolytic activities of natural killer cells." (PMID 22528050, 2012). "Recently, the circulating levels of HSPA1A/B in serum in cancer patients are of interest in both defining prognostic significance and identifying a potential target for new therapeutic strategies, such as radiotherapy." (PMID 24213112, 2011). "Low-level synthesis of HSPA1A can occur in cultured human cells and is also detected in specific tissues from both mice and humans but appears to be upregulated in many cancer cell lines." (PMID 24213112, 2011). "Relatively little is known about circulating serum levels of HSPA1A/B and to date the impact of common cancer treatments on circulating HSPA1A/B has been undefined." (PMID 24213112, 2011). "HSPA1A from resistant cancer cells stimulates an NK-cell antitumor response." (PMID 41369326, 2025). "HSPA1A (Hsp70), in particular, is actively involved in suppressing apoptosis, programmed cell death, which is one of the key mechanisms of the body’s defense against cancer cells." (PMID 41369326, 2025). "Indeed, an in vitro co-culture experiment of CAFs and PDAC cells demonstrated that Pn-ASVs with exon 21 dimerized with heat shock protein 70-1a (HSPA1A) from cancer cells mediated Pn-induced chemoresistance in cancer cells." (PMID 39684914, 2024). "Then, we examined the impact of HSPA1A knockdown on Pn-mediated anti-cancer drug resistance." (PMID 39684914, 2024). "However, it is now well established that HSPA1A translocates to the plasma membrane (PM) and the endo/lysosomal pathway of cancer and stressed cells, and these cells actively export HSPA1A to the extracellular medium (EM)." (PMID 35740982, 2022). "HSPA1A is a molecular chaperone that regulates the survival of stressed and cancer cells." (PMID 35740982, 2022).
cancer (continued). "Our current results further promote the concept that lipid binding is a specific activity of HSPA1A that is increasing under certain conditions, including stress, cancer, and maybe other disease states." (PMID 35740982, 2022). "Therefore, several investigators aim to target the cell surface/PM-localized HspA1A as a novel anti-cancer treatment." (PMID 32825419, 2020). "In contrast, human Hsp70 (HSPA1A/B) is barely detectable in most non‐cancer cells and reaches only about 0.04–0.06 μM upon heat shock, but can reach around 0.7–10 μM in cancer cells." (PMID 32490574, 2020). "The six thermogenes include HSP90AA1 and HSPA4, common in thermoresistance and DAMPs/ICD, DNAJB5, the protein product of which has the highest estimated thermostability, and HSPA1A, HSP90AB1, and BAG1, which are implicated in cancer-relevant pathways (underlined)." (PMID 31814876, 2019). "Activating genes in this branch, first of all TERT, heat shock protein 90 (HSP90AA1, HSP90AB1), importin 7 (IPO7) and p23 (PTGES3) are overexpressed in cancer, while the heat shock protein 70 (HSPA1A) and CHIP ubiquitin ligase (STUB1), both acting as suppressors, are underexpressed." (PMID 31750255, 2019). "In addition to its critical functions as a cytosolic molecular chaperone, HspA1A is also found at the plasma membrane (PM) of stressed and cancer cells." (PMID 30999671, 2019). "Our study also implies that the interaction between KIAA0100 and HSPA1A may be targeted for new drug development to specifically induce anoikis cell death in the cancer cell." (PMID 29867023, 2018). "After 24, 48, and 72 hours, significantly upregulated HSP70 1A [HSPA1A] mRNA expression levels were observed in 5-FU–treated cancer cells at all investigated temperatures (37°C: FD 2.2, FD 2.9, and FD 2.5; 41°C: FD 1.9, FD 3.0, and FD 1.9; 43°C: FD 2.1, FD 3.7, and FD 3.7, respectively) (top)." (PMID 29403306, 2017). "High HSPA1A/B levels in cancer cells serve as hallmarks for poor survival prognostics." (PMID 25847399, 2015). "CNV-TFs TBP and NFYB targeted HSPA2, HSPA8 and HSPA1A respectively, three members of heat shock protein 70 which could inhibit apoptosis in cancer cells through simultaneous and independent mechanisms." (PMID 24897108, 2014). "However, cancer cells isolated from tumors expressed considerably higher levels of HspA1A, in comparison to cancer cell lines." (PMID 22528050, 2012). "Our data may have a practical implication for targeted anticancer therapies based, among other factors, on the inhibition of HspA1A expression in the cancer cells." (PMID 22528050, 2012). "Our current experiments demonstrate that the activation of neutrophils, followed by an increased production of reactive oxygen species, by cancer cells involves the interaction of HspA1A from cancer cells with Toll-like receptors 2 and 4 expressed on the neutrophils’ surface." (PMID 22528050, 2012). "HspA1A located intracellularly seems to be necessary for cancer cell growth and survival." (PMID 22528050, 2012). "In addition, HSPA1A is overexpressed in many types of cancers and helps cancer cells proliferate." (PMID 40236629, 2025). "Additionally, HSPA1A is considered a therapeutic target for cancer therapy." (PMID 40236629, 2025). "The clinical significance of HSPA1A status is unknown in malignant tumors, including BC." (PMID 37231433, 2023). "By downregulating HSPA1A, the body may attempt to limit the growth and progression of cancer cells." (PMID 37993485, 2023). "Although HSPA1A-related small molecules drugs have been developed to target similar signaling path, such drugs may be toxic not only to cancer cells, but also to normal cells due to their inhibitory effects on normal cellular function like protein folding, autophagy, and lysosomal function." (PMID 29867023, 2018).
cancer (continued). "In both cancer types, we observed significant methylation differences in regions around cancer-related genes, such as MUC1 and HSPA1A,37,58 in which it is difficult to detect methylation status with short-read sequencing." (PMID 41187747, 2025). "Among these, PLXNA3, HLA-E, DDX58, IKBKE, HSPA6, SOS2, and HSPA1A stood out, with significantly elevated expression levels in LIHC compared to other cancer types." (PMID 39000042, 2024). "We also investigated that increased some heat shock proteins (HSPs), HSPA1A and HSPA1B were upregulated in advanced cancer." (PMID 38719807, 2024). "The HSP70s family includes constitutively expressed members HSC70 (HSPA8) and stress-inducible member HSP70 (HSPA1A/HSPA1B), which have been demonstrated to control protein maturation and proper folding in cancer cells." (PMID 36773708, 2023). "Heat-shock family genes involved in HSF1 transactivation (e.g. HSPA1A, DNAJB1 and HSP90AB1) were also significantly enriched in this module, which has been shown previously to regulate cancer-mediated fibroblast activation." (PMID 36720863, 2023). "While HSPA1A and UCK2 have been discussed in the context of diseases such as cancer, their involvement in puberty remains to be reported." (PMID 35831802, 2022). "Within the Hsp70 family, HSPA1A and HSPA1B are the closest ones in differing only by two amino acids, but having their own defined and diverse roles, for example, during cancer." (PMID 36286039, 2022). "Through integrative analyses of the consistently up-regulated genes, ARID2 ChIP-seq data and survival-related genes from the cancer genome atlas (TCGA)-LUAD dataset, we found three candidate genes including Hspa1a, Pkm and Tsku." (PMID 34858604, 2021). "Previous studies have shown that HSPs are differentially expressed in different cancers, including HSPA2 and HSPA1A." (PMID 34712697, 2021). "In particular, the TERT branch is affected by p21 (PTGES3) in LS-CRC, while in s-CRC cancers, we observe high influence of heat shock proteins (HSP90AB1 and HSPA1A)." (PMID 31750255, 2019). "In these networks, PTGS2, VDR, RHOB, PIM1, HSPA1L, HSPA1A, and SPHK1 were used as targets for cancer drug development, previously." (PMID 30842898, 2019). "Importantly, among three miRNAs, only miR-570 showed partial complemental with 3′-UTR sequences in not only human HSPA1A and BAG3 but also HSPA1B and HSP90AA1 (highlighted in red), which are involved in cancer progression." (PMID 36114410, 2022). "Hence, cancer cells often resist chemo- and thermo-therapies by over-expressing HSP70 chaperones, HSPA1A in particular." (PMID 33043037, 2020). "Noticeably, most types of aggressive cancer cells resisting chemotherapies express abnormally high constitutive levels of HSPA1A/B without HS." (PMID 25847399, 2015). "In this study we demonstrate that down-regulation of the heat-inducible Hsp70 (HSPA1A/HSPA1B) to less than 10% of its cellular level does not suffice to challenge the different cancer cells tested." (PMID 24265689, 2013). "Interestingly, it has been shown that HSPA1A is required for cancer cell survival under stress conditions but not for cell proliferation and growth." (PMID 29867023, 2018). "Collectively, these findings demonstrate the importance of the interaction between HspA1A and PS in non-apoptotic cells for the protein’s PM-localization, and further solidify the biological significance of HspA1A–lipid interactions, which have important implications in cancer biology." (PMID 30999671, 2019).
infection (17 papers, 2013 to 2026). The state of being infected such as from the introduction of a foreign agent such as serum, vaccine, antigenic substance or organism. "Hspa1a was significantly upregulated in the gills of 8 °C group at 24 h after infection compared to the negligible expression level in 4 °C group." (PMID 39560796, 2024). "In expression analysis, it can be found that dnajb1b, hspa1a, and dnaja1b show very similar changes in expression over time after infection with A. salmonicida and they all have a tendency toward up-regulated expression." (PMID 39063205, 2024). "The level of heat shock 70 (hspa1a) transcripts significantly increased (5.2-fold, p < 0.0001) at 8 °C compared to the control group at 24 h after infection." (PMID 39560796, 2024). "In contrast, Hspa1a and Hspa1b were inhibited throughout infection but increased suddenly at 48 hpi." (PMID 36830716, 2023). "SNP treatment did, indeed, cause chondrocyte apoptosis, and this was significantly inhibited by the overexpression of HSPA1A via infection of Ad-HSPA1A." (PMID 30622281, 2019). "Of these genes, only the upregulation of Hspa1a and Il1a was maintained 24 h after infection, and the expression of the heat shock protein 1 (Hspd1) gene was upregulated." (PMID 30555476, 2018). "dnajb1b and hspa1a were found to have a co-expression trend under infection stresses." (PMID 39063205, 2024). "In addition, dnajb1b and hspa1a show a more consistent expression trend compared to hspa1b, as their expression levels both increase with infection time." (PMID 39063205, 2024). "Under infection, wIRA radiation could restore HSPA1A levels to control levels and alleviate HSP90AA1 increases in keratinocytes, which might have contributed to the slightly improved survival of wIRA-treated, infected keratinocytes." (PMID 34944618, 2021). "Under infection, wIRA radiation could restore HSPA1A transcription to control levels and alleviate HSP90AA1 increases in keratinocytes." (PMID 34944618, 2021). "HSPA1A expression was quantified by Western blot analyses 1 week after infection and screening." (PMID 27279016, 2016). "Notably, extracellular viral titers were significantly reduced, suggesting that HSPA1A silencing impacts viral release and potentially reduces the release of infectious EVs; however, this may simply be a reflection of reduced infection overall." (PMID 41596312, 2026). "Interestingly, in cluster 3 of DEGs between normal + infection group and undernutrition 75% + infection group, hub genes Dnaja1 (0.49-fold change), Hspa1a (0.12-fold change), Hspa1b (0.20-fold change) and Hsph1 (0.35-fold change) were also downregulated in undernutrition 75% + infection group." (PMID 38185681, 2024). "Changes in heat shock protein transcript levels after infection of fibroblasts with S. aureus and treatment with wIRA were observed for HSPD1 as a slight increase and with heating w/o wIRA for HSPA1A as significant enhancement (p < 0.05) compared to infected cells." (PMID 34944618, 2021). "Notably, in the mock transcriptomic data, there are higher levels of sequenced HSPA1A and HSPA1B transcripts in A549 cells compared to MRC-5 cells prior to infection with ChAdOx1 nCoV-19 with the reverse being true for PML transcripts." (PMID 33722288, 2021).
neurodegenerative disease (9 papers, 2011 to 2025). A disorder of the central nervous system characterized by gradual and progressive loss of neural tissue and neurologic function. "HSPB1 and HSPA1A as promising targets involved in the pathological mechanisms of neurodegenerative diseases." (PMID 37735671, 2023). "In CM, the overexpression of HSPA1A may reflect an attempt to counteract the accumulation of misfolded proteins, similar to what is observed in neurodegenerative diseases." (PMID 40149586, 2025). "UBC, RPL4, and HSPA1A were identified as common hub genes, indicating their central role in the intersected network of dysregulated astrocytic genes across multiple neurodegenerative diseases." (PMID 40244314, 2025). "Hspa1a/b encodes for heat shock protein 70 (HSP70-1a and HSP70-1b) that directs proteins for lysosome degradation in the microglia, and this gene has been shown to be upregulated in neurodegenerative diseases." (PMID 38891920, 2024). "Seven genes were observed to be involved in both infections of three coronaviruses and two neurodegenerative diseases, including the HSP90AA1, ALDH2, CAV1, COMT, MTOR, IGF2R and HSPA1A." (PMID 37015947, 2023). "As such, boosting HSP transcription has been considered as a therapeutic strategy for neurodegenerative diseases, but has had limited clinical success 125–128, and has focused particularly on HSPA1A, which is not upregulated in neurons under most conditions 72,125,126." (PMID 38168440, 2023).